MDM2 (MDM2 proto-oncogene)
Diseases named in the same sentence as MDM2 in open-access papers (continued):
Sharing a sentence is not in itself a finding about the gene and the disease.
cancer (continued). "MDM2 (Mouse double minute 2 homolog) is another E3 ligase that is involved in cancer." (PMID 32882786, 2020). "Indeed, Mdm2 is one of the best-studied proteins in relation to cancer development, and is specifically up-regulated in cancers of mesenchymal origin." (PMID 33114139, 2020). "Being a crucial oncogenic molecule, MDM2 is frequently over-expressed in numerous cancers." (PMID 32894144, 2020). "The dramatically increased MDM2 protein may protect cancer cells from Nutlin-3a-induced apoptosis through various oncogenic mechanisms that have been linked to MDM2." (PMID 32629830, 2020). "There is an increasing interest in developing MDM2 inhibitors for cancer prevention and therapy." (PMID 32397368, 2020). "CCNG1 could stimulate and propel PP2A catalytic activity toward E3 ubiquitin-protein ligase (Mdm2), which has increased or abnormal expression in numerous cancer types including OS." (PMID 31779647, 2019). "So far, the greater effect of RG7388 is evidenced by the elevation of PARP cleavage that coincides well with increases in the levels of Bax and Bak, suggesting activation of the intrinsic pathway by this MDM2 inhibitor leading to apoptotic cell death in the cancer cells." (PMID 30700046, 2019).
cancer (continued). "In addition, several interesting individual genes have also emerged, such as DHODH, the highest scoring cancer-specific essential gene and MDM2, which is one of the highest scoring ESC-specific essential genes." (PMID 31889988, 2019). "Overexpression of MDM2 have been shown in various cancer types." (PMID 31528638, 2019). "It indicated that MDM2 is likely to play an important role in the generation and development of cancer and may promote the resistance to targeted therapy and other anti-cancer therapies." (PMID 31440117, 2019). "Finally, while the expression of the cell death inducer MDM2 was decreased in cancer EVs-exposed cells, the expression of the anti-apoptotic factor BCL2L1 was increased." (PMID 31200749, 2019). "From the cancer standpoint, we predict that combining cell cycle arrest with DNA damage repair via the MDM2/HBP1 axis might have therapeutic potential for human cancer." (PMID 30816344, 2019). "Inhibition of MDM2 is obviously a good strategy to fight cancer drug resistance." (PMID 35582716, 2019). "In conclusion, MDM2 amplification and overexpression play a great role in therapeutic resistance and targeting MDM2 might be a novel therapeutic strategy for cancer treatment." (PMID 31440117, 2019). "Several studies demonstrated that MDM2 overexpression increases cancer drug resistance of tumors." (PMID 35582716, 2019). "Similarly, p300 mediated acetylation of MDM2 E3 ligase on Lys182 and Lys185 and stabilize MDM2 in numerous cancers." (PMID 31043584, 2019). "Among them, MDM2 is one of the most important target for cancer treatment." (PMID 31440117, 2019). "Therefore, identifying the exact mechanisms by which MDM2 is impacting cancer progression at the molecular level would offer greater benefits towards treating cancers that are overexpressing MDM2." (PMID 29748481, 2018).
cancer (continued). "Although nutlin-34, the most commonly used mdm2 inhibitor, has cytotoxic effects in some cell types, it frequently induces a reversible cell cycle arrest that could limit its efficacy in cancer treatment." (PMID 29549331, 2018). "Thus, our results suggest that MDM2 inhibition can suppress the paracrine function of the cancer cells." (PMID 29748481, 2018). "Beyond cancer, MDM2 inhibitors might also provide an effective and unexplored strategy to reduce some of the effects of senescent cells in driving aging and age-related pathologies." (PMID 29402901, 2018). "Importantly, human cancers often overexpress MDM2 and MDMX, which can directly contribute to tumorigenesis in addition to perturbing the efficacy of conventional chemotherapy and radiation therapy." (PMID 29460395, 2018). "Furthermore, Lakoma et al11 showed that pharmacologic inhibition of MDM2 is associated with a decrease in hypoxia-inducible factor 1α and VEGF expression in cancer cell lines." (PMID 30148248, 2018). "Additionally, some of the differentially expressed genes in MDM2 overexpressing cancers can be utilized as a significant biomarker in conjunction with their master regulator." (PMID 29748481, 2018). "This study suggests that MDM2 amplification is found in a subset of most cancer diagnoses and that optimization of targeted therapy against MDM2 and immunotherapy might require relevant combinations of drugs." (PMID 30148248, 2018). "For these reasons, MDM2 has posed as an attractive and relevant target for cancer therapy." (PMID 30237864, 2018). "This has spurred the search for optimized combinations of MDM2 inhibitors with other cancer drugs." (PMID 30206211, 2018). "Our findings suggest that MDM2 inhibitors could reduce cancer progression in part by reducing the pro-inflammatory environment created by senescent cells." (PMID 29402901, 2018). "However, continued presence of MDM2 is required for cancer initiation and results in sustained regression of tumors." (PMID 30271790, 2018).
cancer (continued). "Thus, our overall results substantiate the possibility that MDM2 can promote the expression of MMP9 through activation of TNF-α pathway to support the invasive behavior of the cancer cells." (PMID 29748481, 2018). "Our results offer additional confirmation to our speculation that MDM2 can shift the balance of the intracellular events in cancer cells towards pro-angiogenic mechanisms through up-regulation of TNF-α, MMP9, and CXCL10." (PMID 29748481, 2018). "Hence, MDM2 oncogenic activities have been recognized as an essential element in promoting cancer progression." (PMID 29748481, 2018). "Among the 102,878 diverse cancers studied, MDM2 amplification was identified in 3,650 (3.5%)." (PMID 30148248, 2018). "Elevated levels of MDM2 protein are commonly observed in human cancers." (PMID 29137250, 2017). "It is well known that inherited and acquired changes in pre-mRNA splicing play a significant role in human disease development and many cancer-associated genes are regulated by alternative splicing, such as CD44, the Wilms' tumor gene WT1, BRCA1, MDM2, FGFR and kallikrein family members." (PMID 29156833, 2017). "To further explore ADAR1-driven RNA editing events, we performed RESSq-PCR analysis on other cancer-associated loci, including the DNA cytidine deaminase APOBEC3D, antizyme inhibitor 1 (AZIN1), and murine double minute 2 E3 ubiquitin protein ligase (MDM2)." (PMID 29203771, 2017). "Therefore, SAR405838 treatment only induced apoptosis in cancer cells harboring MDM2 amplifications." (PMID 27888811, 2017). "Therefore, numerous studies remain committed to testing novel anti-cancer drugs targeting MDM2 and VEGF, or both simultaneously." (PMID 28274247, 2017).
cancer (continued). "In this light, the aim of this review is to give an updated overview about the state of the art of the clinical evaluation of MDM2/X inhibitor compounds with a special attention to hematological malignancies and to the potential for the management of pediatric cancers." (PMID 28673313, 2017). "We believe that MDM2-VEGF targeting represents a novel strategy for improving cancer outcome." (PMID 28274247, 2017). "In certain cancers, Mdm2 is over-expressed leading to excessive inactivation of p5354." (PMID 29062047, 2017). "Although recent scientific advancements have led to the identification of 72 diverse MDM2 isoforms in various human cancers and normal tissues, the functional roles for many of these spliced variants remain underexplored, and some isoforms lack the potential to be translated into proteins." (PMID 29065514, 2017). "The Mdm2 protein is an emerging therapeutic target for treatment of cancers." (PMID 29065514, 2017). "The suggestion that these extra copies encodeTP53 isoforms that are not subject to MDM2 regulation predicts a fascinating biological perspective and has potential ramifications for consideration for human cancer therapy and longevity." (PMID 29250320, 2017). "We observed significantly enhanced Mdm2 expression in the cancer cells with down-regulated USP48 levels, suggesting that USP48 could contribute to the regulation of Mdm2 expression in human cells." (PMID 28233861, 2017). "In a recently published report by our laboratory, we identified a crucial role for Mdm2 in stemness maintenance and cancer cell survival, via stabilization of H2AK119ub1 and the closely associated trimethylation of histone 3 lysine 27 (H3K27), as detailed below." (PMID 27927750, 2017). "Regardless of the factors that produce these variants of MDM2 in the context of cancers, overexpression of MDM2 isoforms in high-grade tumors have been correlated with poor prognosis." (PMID 29065514, 2017). "If fulvestrant-resistant cancers have up-regulated MDM2 they might be excellent candidates for treatment with MDM2 blocking therapies." (PMID 28615518, 2017).